IL21 (interleukin 21)
Diseases named in the same sentence as IL21 in open-access papers (continued):
Sharing a sentence is not in itself a finding about the gene and the disease.
tumor (continued). "Exposure to IL-21 during in vitro priming has previously been shown to enrich for a population of CD8+ T cells with high affinity recognition of tumor antigen, effector function, and expression of co-stimulatory molecules such as CD28." (PMID 25317334, 2014). "Antitumor activity was observed at all dose levels of IL-21 in combination with sorafenib, with the majority of patients experiencing shrinkage of the target tumor lesions per RECIST." (PMID 24829759, 2014). "Histological analyses suggested that the GM-SCF, IL-21, and Rae-1 genes alone or in combination induced a cellular immune response against H22 tumor cells." (PMID 24350772, 2013). "The anti-tumor activity of IL-21 has also been demonstrated in several mouse tumor models, and was found to be partially or completely dependent upon NK cells and/or CD8 T cells." (PMID 23825648, 2013). "Recent studies in mice have shown that adoptively transferred T cells demonstrated superior in vivo persistence and tumor elimination when pre-treated with either IL-15 or IL-21." (PMID 23402380, 2013). "All 24 tumor samples had an increase in IL-21 mRNA levels, up to 70 fold, while only 12 of 24 samples had an increase in IL-23 mRNA levels, up to 15 fold, compared to matched normal tissue." (PMID 23365642, 2013). "In vitro IL-21 treatment of cells from these tumors induced STAT signaling and was associated with growth arrest and tumor cell apoptosis." (PMID 23825648, 2013). "This is particularly important in the light of a downregulation of NK cells and the immune cells containing interleukin 2, IL-17a (TH17) and IL-21 which suggests the influence of tumor cells on the innate immune system." (PMID 23877403, 2013). "Both pre-clinical and clinical studies have shown that IL-21 has potent anti-tumor effects due to its ability to expand the cytotoxic immune response." (PMID 23109839, 2012). "IL-21 can enhance cytotoxicity to antibody-coated tumor targets, consistent with our finding of high expression of CD16 and functional ADCC in mbIL21-expanded NK cells." (PMID 22279576, 2012). "Pre-clinical data indicate enhanced anti-tumour activity when combining recombinant human interleukin-21 (rIL-21), a class 1 cytokine, with cetuximab, a monoclonal antibody, targeting the epidermal growth factor receptor." (PMID 22315057, 2012). "The specificity of IL-21 activity on tumor cells was tested in vitro with a neutralizing antibody against this cytokine." (PMID 21949734, 2011). "Predictions were in agreement with the validation set readouts in most doses (R2>0.94), collectively demonstrating a moderate dose-dependent decrease in IL-21-mediated tumor eradication." (PMID 22022259, 2011). "Recent evidence for anti-angiogenic effects of IL-21 further complicates its dynamical influence on the tumor microenvironment." (PMID 22022259, 2011). "Our model integrates data from preclinical studies under diverse IL-21 treatment settings, and was validated by extensive experiments in tumor-bearing mice." (PMID 22022259, 2011). "IL-21 mRNA was expressed concomitantly with IL-17 mRNA in tumor-bearing eyes and intracellular expression of IL-17A and IL-21 in infiltrating CD4+ T lymphocytes." (PMID 21949734, 2011). "Our systemic model analysis therefore represents a new effort to identify improved, clinically-appropriate IL-21 therapies, using the preclinical tumor models B16 and RenCa as case studies." (PMID 22022259, 2011). "Experimental models have demonstrated the anti-tumor potential of IL-21, via expansion of tumor specific CD8+ effector T cells and suppression of anti-inflammatory Treg cells." (PMID 20184734, 2010). "CD34-lineage- cells cultured with IL-15 and IL-21 for 4 weeks were assayed for NK activity against NK-sensitive tumour cell targets." (PMID 19712464, 2009). "The antitumor activity of IL-21 has been demonstrated in murine experimental models where direct effects of IL-21 on NK cells were responsible for tumour suppression." (PMID 19712464, 2009).
tumor (continued). "T cells rescued by IL-2, IL-15 and IL-21 killed peptide coated target cells and tumor cells more efficiently than T cells cultured with IL-7 or without cytokine supplementation." (PMID 17406677, 2007). "The cumulative long-term survival of mice from all groups from three experiments followed out to 150 days post tumor inoculation showed that IL-21 + IL-2 treated mice had significantly better survival (46%) compared to all other groups." (PMID 16772043, 2006). "By day 42 previously regressing tumors in a subset of IL-21 + IL-2 treated mice began to grow again, reaching a mean tumor size of 25–50 mm2." (PMID 16772043, 2006). "The combination of IL-21 + IL-15 resulted in prolonged tumor regression and survival out to 32 days." (PMID 16772043, 2006). "Mice treated with the vaccine plus IL-15 or IL-21 alone all died of tumor within 32 days of treatment." (PMID 16772043, 2006). "There have been few published studies describing the anti-tumor effects of recombinant IL-21 in conjunction with hgp10025–33 vaccination in B16F10 tumor-bearing lymphopenic mice receiving naive pmel Tg CD8+ T cells." (PMID 16772043, 2006). "IL-21 alone and IL-2 alone both delayed tumor progression, but only IL-21 significantly augmented long-term survival (20%) compared to the control group." (PMID 16772043, 2006). "At peak expansion (21 days post vaccination), the combination of IL-21 plus IL-2 resulted in a 2- to 3-fold higher absolute number of circulating tumor antigen-specific pmel CD8+ T cells than was stimulated by IL-2 or IL-21 alone." (PMID 16772043, 2006). "In both models, IL-2 and IL-15 delayed tumor growth, but only IL-21 resulted in significant prevention of tumor progression and improved survival beyond 50 days from tumor challenge." (PMID 16772043, 2006). "Having shown that treatment with IL-21+ low-dose IL-2 significantly delayed early tumor growth, we compared the effects of the three different cytokine regimens on long-term tumor regression and overall survival beyond 30 days." (PMID 16772043, 2006). "By day 21, vaccination combined with IL-21 + IL-2 treatment inhibited tumor growth significantly better than vaccination alone (p = 0.0013) and vaccination combined with IL-2 (p = 0.0044) or with IL-21 (p = 0.044)." (PMID 16772043, 2006). "By day 28, vaccination combined with IL-21+ IL-2 again inhibited tumor growth significantly better than vaccination alone (p < 0.0001) and vaccination combined with IL-2 (p = 0.0006) or with IL-21 (p = 0.0033)." (PMID 16772043, 2006). "Seven days later therapy was initiated with 5 daily IP injections (days 14–18 post tumor inoculation) of IL-2 alone, IL-21 alone or both cytokines." (PMID 16772043, 2006). "All surviving mice in the IL-21 + IL-2 test group were tumor-free at day 150-post tumor inoculation." (PMID 16772043, 2006). "IL-21 treatment resulted in an even longer delay in tumor progression, with 50% of animals reaching day 49 with tumors < 200 mm2, and 3/15 mice from the three experiments survived long-term." (PMID 16772043, 2006). "Furthermore, IL-21 is crucial in reducing the expression of programmed cell death protein 1 (PD-1), which helps decrease cell death and strengthens the anti-tumor capabilities of TCR-T cells." (PMID 40308592, 2025). "IL-21, a cytokine implicated in CD8+ Tfc-like responses, peaked at 3 weeks but was absent at 6 weeks, suggesting transient CD8+ Tfc activation that is often associated with B cell help and early tumor immune surveillance." (PMID 41278869, 2025). "Systemic delivery of IL-21 to NB may be limited by the inability to reach adequate concentrations of IL-21 across the entire tumor." (PMID 39895691, 2025). "Larger tumor size was associated with elevated levels of TNF-α (r = 0.290, P = 0.009), TNF-R2 (r = 0.318, P = 0.022), IL-1α (r = 0.309, P = 0.026), IFN-α (r = 0.349, P = 0.007), MIP-1β (r = 0.306, P = 0.031), and IL-21 (r = 0.295, P = 0.032) in VS-CM." (PMID 39923035, 2025).
tumor (continued). "Indeed, anti–PD-1 therapy increased the levels of IL-21 in BALF of tumor-bearing aged mice, which was disrupted by ICOSL blockade, and lung-infiltrating ICOS+CD4+ T cells in anti–PD-1 Ab–treated aged mice had an ability to produce IL-21." (PMID 40198121, 2025). "Furthermore, the combination of IL-21 with tumor-targeting monoclonal antibodies enhances NK cell activity and improves their anti-tumor effects." (PMID 40103828, 2025). "Based on this, we postulated that the serum concentrations of IL-21 and IL-22 might vary depending on the tumour’s molecular subtype and histological grade." (PMID 40729006, 2025). "Sustained STAT3 activation leads to the proliferation of many tumor cells.The widespread expression of IL-21R in immune enables IL-21 to activate macrophage, DCs, NK cells, B cells, NK T cells, CD4+T cells, CD8+ T cells, Treg cells, Th17 cells, follicular helper T cells, etc.." (PMID 40469178, 2025). "Notably, tumor targeting was achieved and shown relevant for the treatment efficacy of bifunctional antibody-fusion proteins with all three cytokines (IL-15, IL-21 and IL-7) in immunocompetent mouse models." (PMID 40370435, 2025). "It is generally believed that IL-21 exerts anti-tumor effects in PC." (PMID 39958351, 2025). "We acknowledge a theoretical risk that lenalidomide’s immune-stimulatory effects—through T-cell activation, restoration of immune-synapse function, and cytokine induction (e.g., IL-21)—could enhance Tfh-cell activity or modify the tumor microenvironment." (PMID 41357603, 2025). "However, the pleiotropic effects of IL-21 on CAR-NK cell-mediated tumor rejection remain underexplored." (PMID 40176196, 2025). "IL-21 may both exert anti-tumour activity, by supporting the activation of the immune response, and promote tumour progression, by influencing the tumour microenvironment, including angiogenesis and tumour cell stimulation." (PMID 40729006, 2025). "The use of feeder cells, such as EBV-LCL which naturally express the ligand for 4-1BB, a stimulatory receptor on NK cells, in combination with the cytokines IL-21 and IL-2, has been shown to be a highly efficient approach for ex vivo expansion of human NK cells with high anti-tumour activity." (PMID 40060948, 2025). "IL-21+ cells were mostly NK cells and T lymphocytes in the tumor stroma." (PMID 40149674, 2025). "We hypothesized that intratumoral delivery of IL-21 by C021 would amplify the local anti-tumor efficacy of anti-ROR1-CAR-NK cells against NB." (PMID 39895691, 2025). "Indeed large-scale manufacturing batches of human NK cells for clinical use commonly use feeder cells (typically a tumor cell line such as K-562) expressing IL-21 and activating ligands." (PMID 40410571, 2025). "Recent research indicates that IL-21 is capable of suppressing tumor growth." (PMID 40821119, 2025). "Early studies indicated that IL-21 inhibits tumor growth by activating NK cells." (PMID 39958351, 2025). "The tumour may affect immune cells and modulate IL-21 and IL-22 secretion independently of natural regulatory mechanisms." (PMID 40729006, 2025). "IL-21 is a pleiotropic cytokine that supports anti-tumour immunity but may also facilitate tumour progression." (PMID 40729006, 2025). "When recombinant human IL-21 was used in combination with the monoclonal antibody cetuximab, which targets the epidermal growth factor receptor, enhanced anti-tumor activity was observed, with serum sCD25 levels increasing in a dose-dependent manner, and 60% of patients achieving stable disease." (PMID 40376002, 2025). "B cells that recognize tumor antigens may promote antitumor immunity via the development of T follicular helper cells and their production of IL-21, which enhances CD8+ T cell effector functions." (PMID 41026527, 2025). "Liposomal IL-4, IL-6, and IL-21 therapies show potential across various tumor types." (PMID 40143046, 2025).
tumor (continued). "This suggests that ablation-induced anti-tumor effects may require the participation of the IL-21/IL-21R signaling pathway." (PMID 38833177, 2024). "Because recombinant IL-21, although promising, provided modest protection against cancer, in recent years new approaches, based on cytokine engineering, are rapidly developing to improve half-life, tumor targeting and reduce side effects." (PMID 38638431, 2024). "To explore whether IL-21 regulates the anti-tumor activity of CAR-NK-92 cells via the PI3K/Akt signaling pathway, we accessed the phosphorylation level of AKT." (PMID 38263004, 2024). "In conclusion, our study demonstrated that IL-21 could enhance the anti-tumor activity of NKG2D CAR-NK cells and increase the release of INF-γ via AKT signaling pathway." (PMID 38263004, 2024). "Additionally, the combination of MWA, IL-21, and PD-1 mAbs demonstrated profound abscopal anti-tumor efficacy." (PMID 38833177, 2024). "Moreover, treatment with a vaccinia virus armed with IL-21 effectively controlled tumor growth and improved survival for colorectal cancer model mice." (PMID 38638431, 2024). "The T follicular helper cell is related to better survival and therapeutic outcomes in NSCLC, which may be because the T follicular helper cell serves as a critical physiological source of IL-21 for CD8 T cell infiltrating the tumor." (PMID 38728242, 2024). "Also, Erb-IL-21 presented much lower toxicity than Erb-IL-2, even at high doses and intraperitoneal treatment with Erb-IL-21 limited the tumor growth in well-established tumor models (MC38-cEGFR, B16-cEGFR, and Ag104Ld-cEGFR)." (PMID 38638431, 2024). "An in vitro study reported an oncolytic adenovirus co-expressing chemokine CCL21 and IL-21 that could selectively replicate in TERTp-positive tumor cells (Ad-CCL21-IL-21 virus) was able to induce direct lysis of tumor cells by cytotoxic T cells." (PMID 38638431, 2024). "In addition, an Erbitux-based IL-21 tumor-targeting fusion protein (Erb-IL-21) can extend the half-life of IL-21, effectively expand cytotoxic T lymphocytes, and improve its anti-tumor efficacy." (PMID 38833177, 2024). "Additionally, IL-21 in combination with IL-2 and IL-15 was used to obtain the central memory tumor infiltrating T-cells from patients with glioblastoma and pancreatic tumors." (PMID 38638431, 2024). "Moreover, the biological effects of IL-21 are also influenced by the presence of other cytokines or signaling molecules in the tumor microenvironment." (PMID 38720319, 2024). "IL-21 receptor is expressed on vascular endothelial cells (ECs) and this might explain the possible role of IL-21 on inhibition of tumor angiogenesis which has been addressed by both in vitro and in vivo studies." (PMID 38638431, 2024). "In addition, our finding suggested that IL-21 mediated the anti-tumor activity of NKG2D CAR-NK-92 cells through the AKT signaling pathway." (PMID 38263004, 2024). "IL21 has also been shown to enhance T cell anti-tumor responses." (PMID 38225288, 2024). "Also, in intravenous B16-F10 tumor model, combination of IL-21 with each of the two antibodies targeting the regulatory receptors induced fewer lung metastases." (PMID 38638431, 2024). "Additionally, IL-21 promotes the differentiation of B cells into plasma cells, which can produce antibodies targeting tumor cells." (PMID 39456897, 2024). "In a previous study, we observed that irradiating OAC tumour biopsy explants ex vivo had favourable effects on the secretome, significantly increasing the secretion of anti-tumour cytokines IL-21 and IL-31 and decreasing the production of a tumour-promoting cytokine IL-23." (PMID 38672174, 2024). "Considering the superior effector function of IL-21-supplemented TCR-T in the tumor coculture assay, the IL-21 signal may help to generate a unique “long-live effector” phenotype of TCR-T." (PMID 38643203, 2024).
tumor (continued). "After injection into the body, N3-NK-NPs could specifically recognize and kill tumor cells, while NPs could continuously release IL-21 on the surface of NK cells, effectively stimulating NK cells while limiting their systemic toxicity." (PMID 38840653, 2024). "Tumor infiltrating lymphocytes (TILs) cultivated in the presence of K562 artificial antigen-presenting cells engineered to secrete IL-21 exhibited a less-differentiated young phenotype and presented superior antitumor activity upon adoptive transfer, without collateral expansion of Tregs." (PMID 38638431, 2024). "However, the relationship between IL-21/IL-21R and IgA in liver or tumor microenvironment is unclear." (PMID 38720319, 2024). "Furthermore, the combination of PD-1 blockade with IL-21 has shown remarkable efficacy in mouse tumor models, largely by enabling enhanced infiltration of CD8 T cells into the tumor." (PMID 38343535, 2024). "Overexpression of both IL-15 and IL-21 has been shown to further enhance anti-tumor effect." (PMID 39039086, 2024). "In CT26 and MC38 tumor models the PD-1Ab21 intraperitoneal administration revealed robust antitumoral effects compared to nontreated group and groups treated with anti-PD-1 antibody or mAb PD-1 plus IL-21 groups." (PMID 38638431, 2024). "Blocking lymphocyte efflux counteracted the anti-tumor effect of MWA combined with IL-21." (PMID 38833177, 2024). "Considering the pivotal role of CD8+ T cells in augmenting MWA's anti-tumor efficacy through IL-21, we categorized CD8+T cells into distinct subtypes, including effector, cycling, IFN-induced, exhausted, and stem-like following the classification method outlined in our previously published articles." (PMID 38833177, 2024). "To understand how IL21 is involved in cancer immunity in humans and mice, we first investigated the cellular origin of IL21 in human cancer tissues and mouse syngeneic tumor models by integrating and analyzing multiple single-cell RNA sequencing (scRNA-seq) datasets." (PMID 37546701, 2023). "A recently published study by our group describes how radiotherapy promotes anti-tumour immunity increasing IL-21 and IL-23 cytokines and suppressing pro-tumourigenic pathways in the tumour microenvironment via downregulating the production of pro-angiogenic mediators." (PMID 35986757, 2023). "Additionally, an alternative approach was reported to use fusion proteins to deliver cytokines to tumor cells by tumor-specific Abs in synergy with NK activating cytokines IL21." (PMID 37190251, 2023). "Tumor growth inhibition has also been demonstrated in C57BL/6 mice treated for 6 days with the intrathecal administration of a vaccine virus (VV) expressing IL-21 called VVLΔTK-STCΔN1L-mil-2." (PMID 37759505, 2023). "Additionally, IL-21 indirectly enhances anti-tumor activity by promoting antibody production by B cells, aiding in targeting and killing tumor cells." (PMID 38090585, 2023). "Furthermore, we utilized scRNA-seq and paired single-cell T-cell receptor sequencing (scTCR-seq) to study synergism between IL21 and PD-1 blockade in the tumor microenvironment (TME)." (PMID 37546701, 2023). "IL-2, IL-15, and IL-21 in the IL-2 cytokine family play a positive role in anti-tumor effects, and IL-4, IL-7 and IL-9 possess pleiotropic functions, with diverse roles in cancer immunity as they can have pro-tumorigenic functions as well as anti-tumorigenic characteristics." (PMID 36936961, 2023). "In tumor-bearing mice, stronger tumor remission was observed with PD-1Ab21 treatment than that with the combination of PD-1 blockade and IL-21 infusion, which was attributed to the increased frequency of TSCM cells and robust expansion of tumor-specific CD8(+) T cells with a memory phenotype." (PMID 38049832, 2023).